MMP3 (matrix metallopeptidase 3)
Diseases named in the same sentence as MMP3 in open-access papers (continued):
Sharing a sentence is not in itself a finding about the gene and the disease.
colorectal cancer (continued). "In colorectal cancer, HDAC11 downregulates MMP3 expression by reducing histone H3K9 acetylation at the MMP promoter, thereby suppressing colorectal cancer metastasis." (PMID 38374872, 2024). "In this study, we conducted differential gene expression analysis on three GEO datasets and confirmed SPP1, MMP1, CXCL8, CXCL1, TIMP1, MMP3, and CXCL10 as core regulatory genes in colorectal cancer through a protein-protein interaction network." (PMID 37842645, 2023). "Results showed that ROCK1, LIMK1, MMP3, and MMP9 mRNA expressions were down-regulated after ALKAL1 silencing in colorectal cancer RKO and SW480 cells." (PMID 33391411, 2021). "Ginsenoside Rh1 (Rh1) inhibited colorectal cancer cell migration and invasion by partial inhibition of MMP1 and MMP3." (PMID 33921173, 2021). "Plasmin activates pro-MMP-3 to MMP-3, which then activates pro-MMP-9 in the promotion of colorectal cancer progression." (PMID 23710449, 2013). "Several pro-angiogenic (VEGF, Ang-2, PIGF, sVCAM-1, MCP-1, MMP-3, CHI3L1, IL-8 and CXCL16) and ECM-degrading (MMP-2 and MMP-7) proteins are known to be elevated after colorectal cancer resection, but in relation to postoperative complications such research remain scarce." (PMID 39167197, 2024). "Therefore, the specific mechanism of action of MMP3 and MMP1 in colorectal cancer needs to be further studied." (PMID 36338624, 2022). "Previous studies have shown that the migration of colorectal cancer cells would be attenuated with downregulating MMP-3, and knockdown either MMP-3 or MMP-13 could repress the invasion and migration of anaplastic thyroid carcinoma cells." (PMID 32711573, 2020). "The tight suppression of MMP-3 (↓ 81.3% KAE, ↓ 83.3% cisplatin), as well as u-Plasminogen Activator/Urokinase (↓ 71.7% KAE, ↓ 74.8% cisplatin), directly impairs ECM degradation, cell migration, and metastatic spread—critical steps in colorectal cancer progression." (PMID 41515404, 2025). "In addition, MMP1, MMP3 and MMP9 polymorphisms were not linked with colorectal cancer susceptibility." (PMID 28445160, 2017). "It has been reported that miR‐200c inhibits MMP‐3 expression, which in turn abolishes ovarian cancer metastasis, downregulates E‐cadherin, and affects the EMT in human renal cell carcinoma, as well as targeting the 3′‐UTR region of jnk2 mRNA to inhibit the metastasis of colorectal cancer." (PMID 28846829, 2017).
ovarian carcinoma (35 papers, 2009 to 2025). A malignant neoplasm originating from the surface ovarian epithelium. "It should be noted that MMP-3 expression in ovarian cancer was associated with the degree of disease according to FIGO—patients in higher grades had higher expression of this enzyme." (PMID 40565125, 2025). "Secondly, the risk of ovarian cancer increased with age in association with MMP3, MMP10, MMP7, TIMP3, POX/PRODH, PYCR1, PYCR3 to indicate degenerative histological changes." (PMID 38397798, 2024). "In our study we showed that high baseline mean MMP3 levels were associated with shortened total survival time among patients with ovarian cancer (p = 0.00006)." (PMID 29304854, 2018). "Moreover, serum MMP3 concentrations have been investigated to meet the criteria of a good diagnostic test for ovarian cancer." (PMID 32922541, 2020). "In the context of cisplatin-resistant ovarian cancer, targeting MMP3 with siRNA offers a promising therapeutic approach." (PMID 40362252, 2025). "Our study identified MMP3 as a key player in cisplatin resistance, demonstrating that MMP3 knockdown reduces cell viability, proliferation, and invasion in resistant ovarian cancer cells, with enhanced effects when combined with cisplatin." (PMID 40362252, 2025). "Liposomal MMP3-siRNA was used to enhance the stability, specificity, and delivery efficiency of siRNA in ovarian cancer cells." (PMID 40362252, 2025). "The complex interaction between genotype and phenotype in cancer progression necessitates further functional studies to dissect the precise molecular mechanisms governing MMP-3 expression and activity in ovarian cancer." (PMID 40564842, 2025). "The overexpression of MMP3 and its function as a prognostic factor have been reported in breast, cervical, renal, colorectal, gastric, lung, melanoma, pancreatic, and ovarian carcinomas." (PMID 40362252, 2025). "Multiple studies have shown that MMP3 is pivotal for the invasion of many solid tumors, for instance, gastric cancer 16, ovarian cancer." (PMID 35399729, 2022). "Markedly increased abundance of the MMP-3 transcript is found in chicken ovarian cancer and the expression pattern is relatively similar to that of MMPs in human cancer." (PMID 34360823, 2021). "Another new finding was that we identified MMP-3 as a novel bonafide target of miR-18a in ovarian cancer cells." (PMID 33392094, 2020). "First, we measured the MMP-3 protein levels in a panel of ovarian cancer cells and observed higher levels of this protein in cisplatin-resistant compared with cisplatin-sensitive cells." (PMID 33392094, 2020). "Small-interfering RNA (siRNA)-mediated silencing of MMP-3 reduced cell viability, cell growth, and the invasiveness potential of cisplatin-resistant ovarian cancer cells." (PMID 33392094, 2020). "Nonetheless, therapeutic experiments are needed before proposing MMP-3 as a therapeutic target for ovarian cancer treatment." (PMID 33392094, 2020). "Here, we showed that siRNA-mediated MMP-3 silencing reduced cell viability, cell growth, and invasion of cisplatin-resistant ovarian cancer." (PMID 33392094, 2020). "Taken together, this study proposes miR-18a as a promising therapeutic target in cisplatin-resistant ovarian cancer and validates MMP-3 as a direct miR-18a target in cisplatin-resistant ovarian cancer cells." (PMID 33392094, 2020). "As MMP-3 is a direct miR-18a-regulated gene in ovarian cancer, MMP-3 is also a promising target for siRNA-based therapies in ovarian cancer and other malignancies." (PMID 33392094, 2020). "Starting with several potential target genes, we confirmed only MMP-3 as a direct miR-18a target in ovarian cancer cells." (PMID 33392094, 2020). "Together, our results suggest the possibility that SC66 inhibits invasiveness of ovarian cancer cells through the TGF-β1/Ets-1/MMP3 axis." (PMID 30975980, 2019). "Histological analysis demonstrated that MMP-3 expression and activity were enhanced in the stromal cells surrounding the ovarian cancer cells." (PMID 29390034, 2018).
ovarian carcinoma (continued). "Although several MMPs have been studied in ovarian cancer, few studies have focused on MMP-3 in EOC." (PMID 29390034, 2018). "Among them, MMP-3 (stromelysin-1) is overexpressed in various tumor types, and its activation has been reported in ovarian cancer." (PMID 29390034, 2018). "The nature of its enzyme activity and expression pattern implies that MMP-3 plays critical role during an early phase of tumor progression when ovarian cancer cells interact with fibroblasts." (PMID 29390034, 2018). "Increased expression of MMP3 has also been reported in oxaliplatin-resistant ovarian carcinoma cell line A2780/C10." (PMID 24804215, 2014). "Other genes linked to ovarian cancer were also identified as TAF4B targets in TAF4B-overexpressing SIGCs, including c-Jun, matrix metalloproteinase-3 (Mmp-3), and Fibronectin-1 (Fn1)." (PMID 24653979, 2014). "The co-IP of CCDC22 with MMP3 in cisplatin-resistant OVCAR3CIS cells highlights a potentially significant interaction that may contribute to cisplatin resistance in ovarian cancer cells." (PMID 40362252, 2025). "MMP-3 concentrations in ovarian cancer patients and women with benign lesions (9367.86 pg/mL)." (PMID 40565125, 2025). "MMP-3 expression was found in all histological types of ovarian cancer." (PMID 40565125, 2025). "The purpose of the present study was to determine the diagnostic utility of selected MMPs, MMP-2, MMP-3, MMP-11 and MMP-26, as new biomarkers in patients with ovarian cancer and to compare the results obtained with routinely determined markers CA125 and HE4 and the ROMA algorithm." (PMID 38892452, 2024). "In fact, public microarray data from our laboratory (Gene Expression Omnibus accession) has shown that cisplatin-resistant ovarian cancer cells in the A2780CP20 cell line expressed higher MMP3 levels than their cisplatin-sensitive counterparts of the A2780 cell line." (PMID 35008958, 2022). "For example, matrix metalloproteinase 3 (MMP3), one of the most increased transcripts upon RBPMS knockout, has been linked with the metastatic potential of various cancer types as well as cisplatin resistance in ovarian cancer cells." (PMID 35008958, 2022). "Therefore, it suggests that the cell type-specific expression of the MMP-3 gene renders it as a unique marker for epithelial ovarian cancer and indicates the significant role for MMP-3 in ovarian cancer development in hens." (PMID 34360823, 2021). "In this study, we explored the biological function of MMP-3 in cisplatin-resistant ovarian cancer." (PMID 33392094, 2020). "In addition, miR-200 overexpression significantly inhibits ovarian cancer cell invasiveness and metastasis by downregulating MMP3, possibly through ZEB1/pSMAD3 signaling." (PMID 32256980, 2020). "Finally, we used siRNAs to silence MMP-3 and observed a significant reduction in cell growth, cell viability, and the invasion ability of cisplatin-resistant ovarian cancer cells." (PMID 33392094, 2020). "Together these results suggest that MMP-3 is a direct target of miR-18a in ovarian cancer cells." (PMID 33392094, 2020). "This portion of MMP-3 could promote the activation of genes involved in the drug resistance of ovarian cancer cells." (PMID 33392094, 2020). "Among these studies, 8 studies with 2 polymorphisms (5 studies for MMP1 rs1799750, 3 studies for MMP3 rs34093618) involving 1019 ovarian cancer cases and 1609 controls could be quantitatively synthesized for meta-analysis." (PMID 28957437, 2017). "Furthermore, previous reports have demonstrated that miR-200c could suppress metastasis, via mechanisms such as inhibition of MMP-3 expression to abolish ovarian cancer metastasis and downregulation of E-cadherin to affect EMT in human renal cell carcinoma." (PMID 31240993, 2019). "It is possible that the 5A/6A polymorphism of the MMP3 gene may not be directly associated with development of ovarian cancer." (PMID 30381735, 2018).
ovarian carcinoma (continued). "The presence of MMP-7, MMP-26, MMP-3, MMP-10, and MMP-11 expression has been previously confirmed in biopsy material from ovarian cancer patients." (PMID 41007705, 2025). "In conclusion, we are the first team to study the significance of MMP-2, MMP-3, MMP-11 and MMP-26 as new markers of ovarian cancer in comparison not only to HE4 and CA125, but also to the ROMA algorithm." (PMID 38892452, 2024). "DAB2 expression had significant positive correlations with mesenchymal markers (ZEB2, TGFβ1, SNAI2, ZEB1, FN1, MMP2, TWIST1 and MMP3) and CSC markers (CD44 and MYD88) in ovarian cancer cell lines (CCLE) and tissues (TCGA: RNA sequencing and microarray)." (PMID 37815603, 2023). "Although MMP-3 has been studied in several cancers, there are limited reports of the role of MMP-3 in ovarian cancer." (PMID 33392094, 2020). "As we found that MMP-3 is a direct target of miR-18a-5p, we further assessed the biological effects of targeting MMP-3 in cisplatin-resistant ovarian cancer." (PMID 33392094, 2020). "Aim of this research was to assess MMP3 and TIMP3 as prognostic factors among patients with ovarian cancer." (PMID 29304854, 2018). "Thus, the analysis of early-stage MMP expression, including MMP-3 expression, may serve as a potential molecular target for imaging prior to cancer metastasis and progression, especially given the importance of the tumor stroma in ovarian cancer progression." (PMID 29390034, 2018). "Mean concentration of MMP3 (20836 pg/ml) marker as well as CA125 and HE4 (798 U/ml / 423 pmol/L) in the group of ovarian cancer patients was significantly higher compared to mean concentrations of those markers among patients with endometrial cysts." (PMID 29304854, 2018). "The MMP-2, MMP-3, and MMP-9 expression levels were next examined in the cocultivation of SKOV3 and WS1 to mimic the interaction of ovarian cancer cell with stromal cells." (PMID 29390034, 2018). "In a previous study using ovarian cancer cell lines and ovarian orthotopic tumor models, FILIP1L decreased MMP-3, -7, and -9 levels and inhibited cancer cell migration and invasion both in vitro and in vivo." (PMID 27750216, 2016). "Additionally, stromelysin MMP3 was unchanged, while membrane-type MMP (MMP14) was lower in ovarian cancer as compared to control samples." (PMID 38397798, 2024). "The serum levels of MMP-3 and TIMP-3 correlate with survival in ovarian cancer." (PMID 35629249, 2022). "However, mean MMP3, HE4, and CA125 protein levels were significantly higher in the group of patients with ovarian cancer compared to patients with benign ovarian cysts." (PMID 29304854, 2018). "So far, there is no available information regarding serum level of MMP3 in patients with ovarian cancer and its potential prognostic role." (PMID 29304854, 2018). "Notably, MMP3, alternatively named stromelysin-1, is regarded as a stromal MMP that exerts tumor-promoting effects in mammary, colorectal, and ovarian cancers." (PMID 26992208, 2016). "It is noteworthy to speculate whether some proteases including MMP-3, ADAM9 and MT1-MMP are activated in thyroid carcinoma as well as in hepatoma and ovarian carcinoma." (PMID 23917679, 2013). "In summary, our findings highlight that combination therapy involving liposomal MMP3-siRNA and cisplatin effectively mitigates tumor growth in a cisplatin-resistant mouse model of HGSOC but raises concerns about the feasibility of targeting MMP3 alone in patients with ovarian cancer." (PMID 40362252, 2025). "Therefore, the aim of this study was to evaluate the concentrations and diagnostic usefulness of selected enzymes from the matrilysin group (MMP-7, MMP-26) and stromelysins (MMP-3 and MMP-10) in the most common histological type of ovarian cancer—the serous type." (PMID 40565125, 2025). "MMP-2, MMP-3, MMP-11 and MMP-26 have not shown potential as stand-alone biochemical markers in ovarian cancer diagnosis." (PMID 38892452, 2024).
ovarian carcinoma (continued). "In the A2780 ovarian cancer cell line, MT2-MMP expression was detectable by RT-PCR, but there was no expression of other MMPs, including MMP-3, -7, -9 and MT1-MMP, which reportedly correlate with EMT." (PMID 27374080, 2016). "In the ovarian cancer tissues, further significant positive correlations were observed between DAB2 and CSC markers (CD34, ALDH1A1, CD117 (Kit)) and mesenchymal markers (MMP9, SNAI1 and MMP3) and negative correlations with mesenchymal markers (CDH2, FOXC2 and SOX10)." (PMID 37815603, 2023).
Stroke (33 papers, 2011 to 2025). Sudden impairment of blood flow to a part of the brain due to occlusion or rupture of an artery to the brain. "Our study is the first to utilize RNA-seq to identify altered gene signatures and pathways associated with improved subacute stroke phase outcome in MMP-3 KO mice." (PMID 39000490, 2024). "GSEA of our transcriptomic data revealed that MMP-3 deletion significantly downregulated expression of genes in the hallmark inflammation gene set during the subacute stroke phase." (PMID 39000490, 2024). "Hierarchical clustering analysis of differentially expressed genes (DEGs) in MMP-3 KO mouse stroke brains revealed decreased expression of genes encoding TNF receptors and proinflammatory cytokines/chemokines and their receptors in both sexes." (PMID 39000490, 2024). "MMP-3 deficient mice exhibit reduced tPA-induced HT after stroke, and MMP-3 exacerbates HT in hyperglycemic rats." (PMID 39000490, 2024). "Nevertheless, apoptosis results in a significant amount of tissue loss following stroke, and our results show that MMP-3 inhibition decreases apoptotic signatures and infarct size in the brain post-MCAO." (PMID 39000490, 2024). "To identify possible mechanisms underlying MMP-3 KO’s effect on reducing stroke infarct volume, we performed additional clustering analysis of data from four samples each of MMP-3 KO and WT stroke brains." (PMID 39000490, 2024). "Overall, female brains had more extensive downregulation of hallmark inflammation genes in the subacute stroke phase upon MMP-3 KO when compared to their MMP-3 KO male counterparts." (PMID 39000490, 2024). "We also observed sex-specific alterations in other EndMT-associated genes; male MMP-3 KO stroke brains showed downregulation of Tgfbr3 and the major EMT-associated transcription factor Snai2." (PMID 39000490, 2024). "Injury-induced MMP-3 is upregulated within several hours after stroke, suggesting association with the initial opening of the BBB." (PMID 34299322, 2021). "Downregulation of intrinsic apoptotic gene expression by MMP-3 KO may reduce infarct size after stroke by limiting IR injury and neuronal loss from intrinsic apoptosis induced by oxygen and glucose deprivation." (PMID 39000490, 2024). "The third peak for MMP3 in the 5q12 region is linked to low density lipoprotein size and stroke." (PMID 23936524, 2013). "We performed RNA-seq of mouse brain tissue harvested at 48 h post-stroke to investigate the effect of MMP-3 KO on differential gene expression at a global level." (PMID 39000490, 2024). "We compared the transcriptomes of male MMP-3 KO mouse stroke brains to those of male WT stroke brains (MMP-3 KO MCAO vs. WT MCAO)." (PMID 39000490, 2024). "Overall, our results highlight MMP-3 as an attractive therapeutic target to improve stroke outcome and our study warrants further investigation of MMP-3′s role in stroke pathophysiology." (PMID 39000490, 2024). "One translational study demonstrated that t-PA treatment selectively induced MMP-3 expression in endothelial cells within the ischemic-damaged area in a mouse stroke model." (PMID 39273389, 2024). "We observed slightly higher MMP-3 TPM values in female wild-type stroke brains compared to male wild-type stroke brains (Figure A4A)." (PMID 39000490, 2024). "We further analyzed DEGs to identify enriched or depleted biological pathways in MMP-3 KO mouse stroke brains." (PMID 39000490, 2024). "For instance, MMP-3 KO decreased Snai1 expression to a greater extent in female stroke brains (Log2FC = −1.91, FDR = 1.01e−8) than in male stroke brains (Log2FC = −0.99, FDR = 0.058)." (PMID 39000490, 2024). "Key EMT-related genes that were downregulated upon MMP-3 KO in male stroke brains included Fbn1, Fbln1, Tgfb1, Tgfbr3, Snai2, and Fgf2." (PMID 39000490, 2024). "Male MMP-3 KO stroke brains also exhibited downregulation of apoptosis-related genes such as Casp9, Casp7, Bmf, Casp1, Bid, Casp6, Casp3, Casp2, Fas, Casp4, and Casp8." (PMID 39000490, 2024).